ASB14 (ankyrin repeat and SOCS box containing 14)
Description:
May be a substrate-recognition component of a SCF-like ECS (Elongin-Cullin-SOCS-box protein) E3 ubiquitin-protein ligase complex which mediates the ubiquitination and subsequent proteasomal degradation of target proteins. Plays a role in the inhibition of cardiomyocyte nuclear proliferation by mediating the ubiquitination and degradation of MAPRE2.
Synonyms: DKFZp313L0121
Tractability: No criterion of Open Targets' tractability assessment is met for any kind of drug.
Gene: Protein-coding gene on chromosome 3 (57,268,342 to 57,292,685, reverse strand). Ensembl gene ENSG00000239388.
Subcellular location (Human Protein Atlas): Cytosol
Pathways (Reactome):
Immune System: Antigen processing: Ubiquitination & Proteasome degradation
Metabolism of proteins: Neddylation
Gene Ontology:
Biological process: intracellular signal transduction; protein ubiquitination
Cellular component: cytosol
Genetic constraint (gnomAD): Loss-of-function variants: 60 observed, 55.11 expected, observed/expected ratio (o/e) 1.09, 90% interval 0.88 to 1.35. The upper end of that interval is the gene's LOEUF score, 1.35, which puts it in group 5 of 6, group 1 being the genes least tolerant of losing a copy. Missense variants: 694 observed, 721.01 expected, observed/expected ratio (o/e) 0.96, 90% interval 0.9 to 1.02. Synonymous variants: 247 observed, 266.44 expected, observed/expected ratio (o/e) 0.93, 90% interval 0.83 to 1.03.
Homologues: Orthologues: chimpanzee ASB14 (99% identical), macaque ASB14 (98% identical), dog ASB14 (90% identical), pig ASB14 (90% identical), guinea pig ASB14 (84% identical), mouse Asb14 (83% identical), rat Asb14 (83% identical), rabbit ASB14 (81% identical), tropical clawed frog asb14 (66% identical), zebrafish asb14b (57% identical), zebrafish asb14a (50% identical). Paralogues in human: ASB15 (50% identical), ASB3 (26% identical), ASB10 (19% identical), ASB16 (19% identical), ASB18 (18% identical), MPHOSPH8 (18% identical), ASB4 (16% identical).
Diseases named in the same sentence as ASB14 in open-access papers:
ASB14 is named in the same sentence as 3 diseases in open-access papers, as found by Europe PMC text mining. Sharing a sentence is not in itself a finding about the gene and the disease. The quoted sentences say what the papers report.
heart failure (2 papers, 2019 to 2025). Inability of the heart to pump blood at an adequate rate to meet tissue metabolic requirements. "Biological process functional analysis indicated that ASB14 may be associated with heart failure through the regulation of protein ubiquitination, which requires experimental validation." (PMID 31393969, 2019). "Research has suggested three potential biomarker genes (ASB14, CD163, and CCL5) associated with heart failure through the traditional protein–protein interaction algorithm." (PMID 40297163, 2025).
epilepsy (1 paper, 2020). A brain disorder characterized by episodes of abnormally increased neuronal discharge resulting in transient episodes of sensory or motor neurological dysfunction, or psychic dysfunction. "Our study nevertheless identifies high-impact variations in the Asb14, Msh3 and Arhgef38 genes, with important functional consequences in the resulting proteins, albeit with no known relationship with any type of epilepsy." (PMID 32168507, 2020). "Protein analysis of the other two genes with high- impact variants, Asb14 and Arhgef38, also predicts changes in their function, yet neither ASB14 (ankyrin repeat and SOCS box containing 14) nor ARHGEF38 have been associated with any type or case of epilepsy." (PMID 32168507, 2020).
ASB14 also shares sentences with these, for which no sentence is quoted: tumours (1 paper).